SNHG15 (small nucleolar RNA host gene 15)
Diseases named in the same sentence as SNHG15 in open-access papers (continued):
Sharing a sentence is not in itself a finding about the gene and the disease.
cancer (continued). "We provide an overview of current evidence concerning the functional role, mechanistic models and clinical utilities of SNHG15 in human cancers in this review." (PMID 31774607, 2020). "Meanwhile, more animal experiments are needed to verify the role of SNHG15 in cancer growth and metastasis in vivo." (PMID 31774607, 2020). "SNHG15 was significantly upregulated in seven cancers and elevated expression of SNHG15 indicated shorter OS and DFS in five malignancies based on the validation using the GEPIA cohort." (PMID 33243205, 2020). "Long noncoding RNA small nucleolar RNA host gene 15 (SNHG15) has been reported to play an oncogenic role in many cancers." (PMID 33817274, 2020). "The present study is the first meta-analysis exploring the connection between the abnormal expression of SNHG15 and cancer prognosis." (PMID 32633324, 2020). "More high-quality and large-sample studies are required to further confirm the prognostic role of SNHG15 in cancer." (PMID 32733556, 2020). "A human homolog of this gene, SNHG15, has been studied in cancer, showing upregulated expression in multiple tumor tissues or cells and it promotes cancer cell proliferation and migration by serving as a sponge for miRNAs27–29." (PMID 32483152, 2020). "In this review, we aim to summarize the latest knowledge about the characteristics of SNHG15 in the biological effects and molecular mechanism of human cancers and further debate the prognostic and therapeutic values of SNHG15 in human cancers." (PMID 31774607, 2020). "To further understand the molecular mechanism of SNHG15 overexpression affecting the prognosis of various cancers, we predicted its possible biological function and involved signaling pathways of SNHG15 using six online databases." (PMID 33243205, 2020). "SNHG15 is one of the newly discovered popular lncRNAs involved in the development and progression of many malignant tumors." (PMID 32733556, 2020). "Since then, a large number of studies have reported that SNHG15 is highly expressed in various malignant tumors, including GC, BC, CRC, HCC, NSCLC, TC, and OV." (PMID 32733556, 2020). "Although the prognostic value of lncRNA small nucleolar RNA host gene 15 (SNHG15) expression in cancers has been evaluated in many studies, the results remain controversial." (PMID 32733556, 2020). "SNHG15, a promising new cancer-related lncRNA, has been found to be upregulated in a diverse array of malignant tumours." (PMID 33243205, 2020). "This meta-analysis aimed to clarify the role of SNHG15 in the prognosis of different cancer patients." (PMID 32733556, 2020). "Detailed molecular biological mechanisms between the abnormal expression of SNHG15 and the development of cancers were also discussed and summarized." (PMID 32633324, 2020). "Consistent with our results, SNHG3 and SNHG15 have been reported to be significantly upregulated in several types of cancer." (PMID 32126023, 2020). "In order to further confirm the worse prognostic role of SNHG15 in cancers, we also accessed TCGA cohort, and the high expression of SNHG15 in the most of tumor tissues and bad prognostic factor of SNHG15 in various cancers was identified." (PMID 32633324, 2020). "The high expression of SNHG15 was indicative of a significantly poor OS of cancer patients (HR = 1.96, 95% CI = 1.55–2.47, P < 0.00001)." (PMID 32733556, 2020). "In order to obtain more information about SNHG15 function, Ingenuity Pathway Analysis (IPA) was performed, showing that the genes affected by SNHG15 knockdown are preferentially associated to cancer as well as cell death and survival." (PMID 31014355, 2019). "Thus, further studies on the molecular mechanisms by which SNHG15 mediates cancer progression can provide new insight in the clinical prognosis and treatment of cancer patients." (PMID 39519115, 2024).
cancer (continued). "Overexpressed SNHG15 could promote the occurrence of drug resistance in tumors and reduce the sensitivity of cancer cells to chemotherapy drugs, suggesting its potential as a crucial prognostic factor to predict tumor drug resistance." (PMID 37056344, 2023). "In a nutshell, this finding elucidated a plausible mechanism responsible for the constitutive activation of AKT-mTOR signaling during tumor promotion of OC, supporting the notion that SNHG15 might be a novel target for clinical treatment for cancer patients." (PMID 37056344, 2023). "Thus, subsequent prospective studies with high-quality and large-sample sizes were warranted to further confirm the prognostic role of SNHG15 in cancer." (PMID 37056344, 2023). "Overall, SNHG15 was up-regulated in drug-resistant cancer tissues and cell lines." (PMID 37056344, 2023). "Nevertheless, SNHG15 was determined to be positively tied with unfavorable clinical parameters, resistance to therapy, and poor prognosis, revealing its potential as a promising biomarker for cancer diagnosis and treatment." (PMID 37056344, 2023). "Its human orthologue SNHG15, which we identified to be similarly diminished in expression after ephrinA5-Fc stimulation, has been reported to be upregulated in multiple types of cancer." (PMID 37880732, 2023). "SNHG15 has been demonstrated to be oncogenic in many kinds of cancers, however the mechanism of SNHG15 in LUAD cisplatin (DDP) resistance remains unclear." (PMID 36864456, 2023). "More interesting was that the SNHG15 expression appears to be differentially modulated in different cancer types and correlates with tumorigenesis, tumor aggressiveness, and stage of cancer, which makes it a candidate for cancer therapies." (PMID 37056344, 2023). "Suppression of SNHG15 increased the proportion of cells in the G0/G1 phase and apoptotic rate, which suggests that cell death eventually occurred through cell cycle arrest and subsequent apoptosis of cancer cells." (PMID 37056344, 2023). "We have selected extensive literature focused on SNHG15 from electronic databases, including studies relevant to its clinical significance and the critical events in cancer-related processes such as cell proliferation, apoptosis, autophagy, metastasis, and drug resistance." (PMID 37056344, 2023). "SNHG15 is located on 7p13 and it is known to play a critical role in several cancers as oncogene, and so it could be used as an adverse prognostic biomarker." (PMID 35629174, 2022). "SNHG15 was previously reported to be dysregulated in various types of cancers." (PMID 34980176, 2022). "Although SNHG15 has been investigated in other cancers, the role of SNHG15 and the molecular mechanisms in GC remains unclear." (PMID 33899079, 2021). "SNHG15 usually regulated the expression of target gene via miRNA in cancers." (PMID 34734088, 2021). "Thus, we constructed a ceRNA network to assess the potential function and molecular mechanism of SNHG15 in cancers." (PMID 33243205, 2020). "In addition, an abnormal expression of SNHG15 was reported with a marked relationship with cancer prognosis." (PMID 32633324, 2020). "Further functional prediction indicated that SNHG15 may participate in some cancer-related pathways." (PMID 33243205, 2020). "For example, SNHG15 was reported to be significantly upregulated in tumors and enhanced SNHG15 expression could be a promising biomarker for cancer diagnosis, prognosis or treatment." (PMID 32041570, 2020). "SNHG15 also influenced a series of biological behaviors of tumor cells, and could therefore serve as a potential indicator for cancer prognosis." (PMID 32633324, 2020). "Taken together, these results indicate that SNHG15 could serve as a biological modulator and novel biomarker of poor prognosis in cancer patients." (PMID 33243205, 2020). "Better understanding of the mechanistic model of SNHG15 in human cancers may give new insight into cancer pathogenesis and lncRNA‐based therapeutics." (PMID 31774607, 2020).
cancer (continued). "Dysregulation of SNHG15 has been revealed to be dramatically correlated with advanced clinicopathological factors and predicts poor prognosis, suggesting its potential clinical value as a promising biomarker and therapeutic target for cancer patients." (PMID 31774607, 2020). "Upregulation of lncRNA SNHG15 was notably associated with worse prognosis and clinical features, suggesting that SNHG15 might serve as a novel prognostic factor in various cancers." (PMID 33243205, 2020). "Small nucleolar RNA host gene 15 (SNHG15) was recently identified as a cancer‐related lncRNA." (PMID 30945457, 2019). "Among them, aberrant expression of SNHG14 and SNHG15 have been discovered in cancers, expression of LINC00667 was proved as a biomarker to predict relapse free survival in patients with small hepatocellular carcinoma, most recently, the roles of VLDLR-AS1 and TNRC6C-AS1 in PTC have been studied." (PMID 31372094, 2019). "In addition to its well-documented action as a competitively endogenous RNA (ceRNA) sponging miRNAs in human cancers, SNHG15 was reported to act in the nucleus in concert with EZH2 (Enhancer of zeste homolog 2), which is known to catalyze repressive trimethylation at histone 3 (H3K27me3)." (PMID 37880732, 2023). "This could be mediated by the ephrinA5-dependent transcriptional repression of an important cancer-related lncRNA, namely Snhg15, which might lead to the increased expression of cancer-relevant protein-coding genes, putatively by the loss of Snhg15 triplex binding in gene promoters." (PMID 33572758, 2021). "In addition to its function as a competitively endogenous RNA (ceRNA), sponging miRNA in human cancers, Snhg15 was described to be localized and to act in the nucleus, e.g., by interacting with EZH2 that catalyzes repressive trimethylation at histone 3 (H3K27me3)." (PMID 33572758, 2021). "Thus, ephrinA5 could modulate the transcription of cancer-related genes by acting on Snhg15 expression as a key lncRNA." (PMID 33572758, 2021). "Furthermore, SNHG15 was found to be highly expressed in patients with type II cancers than patients with type I cancers indicating that it could distinguish between type I and type II OC." (PMID 32854207, 2020). "Therefore, SNHG15 is closely related to various biological behaviors of tumor cells and may serve as a potential therapeutic target and an indicator for cancer prognosis." (PMID 32633324, 2020). "In the cytoplasm, SNHG15 can also act as the competing endogenous RNA and competitively bind to a variety of microRNAs, influence the expression of multiple invasion related proteins, and thereby promote the proliferation, invasion, and migration of malignant tumor cells." (PMID 32733556, 2020). "SNHG15, hsa.miR.130a.3p, PTTG1, INSR and HMMR were described in a ccRCC environment, exhibiting the higher expression that induces metastasis and promotes cancer development." (PMID 38673800, 2024). "However, SNHG15 has never been linked to gefitinib in cancer." (PMID 32655137, 2020). "Therefore, we meta-analyzed all relevant publications and TCGA database to achieve a comprehensive understanding of the relationship between SNHG15 expression and cancer patient prognosis and evaluated whether SNHG15 could be a potential biomarker for the prognosis of cancer patients." (PMID 32733556, 2020). "In some cancers, including ACC, KIRC, MESO, and UVM, SNHG15 overexpression indicated shorter OS." (PMID 33243205, 2020). "In addition, the high expression level of SNHG15 was closely related to the advanced characteristics of cancer, indicating that patients without these advanced characteristics may be prime candidates for chemotherapy." (PMID 32733556, 2020).
tumor (37 papers, 2017 to 2025). "We explored the literature on the signaling pathways involved in tumor development for SNHG15 to identify future serve as an early diagnostic biomarker or as a target for gene therapy or other curative treatments." (PMID 37056344, 2023). "The downregulation of SNHG15 and its associated miRNA network overexpression inhibited tumor progression, suggesting SNHG15 as a promising therapeutic target." (PMID 37056344, 2023). "In terms of RFS, advanced tumor stage/pathological stage/histological grade, metastasis and increased SNHG15 expression were potential risk factors of shorter RFS." (PMID 32126023, 2020). "The tumor weight declined under SNHG15 deficiency or gefitinib treatment, and SNHG15 silence also further reduced the tumor weight that was decreased by gefitinib." (PMID 32655137, 2020). "In this study, we reported that SNHG15 expression was also upregulated in PC tissues, and its overexpression was remarkably associated with tumor size, tumor node metastasis (TNM) stage and lymph node metastasis in patients with PC." (PMID 29137412, 2017). "It was shown that the aberrant expression of SNHG15 was closely associated with tumor prognosis." (PMID 37056344, 2023). "Accordingly, the potential molecular mechanism involved in tumour progression may be investigated in the future to better understand the association between altered SNHG15 expression and poor prognosis." (PMID 33243205, 2020). "In this study, we found that SNHG15 was highly expressed in human BC, and upregulated SNHG15 was correlated with large tumor size and advanced TNM stage." (PMID 40959095, 2025). "According to the results of cell cycle analysis, knocking down the expression of SNHG15 resulted in its blockage in the S phase, which in turn inhibited the proliferation of tumor cells." (PMID 38526609, 2024). "Meanwhile, the in vitro cell experiment results also suggested that down-regulating the expression of SNHG15 can inhibit the proliferation and migration of tumor cells." (PMID 38526609, 2024). "To verify the distribution and functional mechanisms of SNHG15 in WT, we further analyzed the results at the single cell level and found that SNHG15 was expressed in both tumor and immune cells." (PMID 38526609, 2024). "SNHG15 expression was significantly increased in liver cancer tissues and cell lines, whereas its downregulation inhibited in vitro tumor cell proliferation." (PMID 37056344, 2023). "We performed qRT-PCR to assess the SNHG15 expression in tumor tissues, and found that sh-SNHG15 treatment down-regulated SNHG15 in mice without or with DDP treatment." (PMID 36864456, 2023). "Yet, RNA immunoprecipitation (RIP) assays have an SNHG15 interaction with EZH2 to repress tumor suppressor genes via EZH2-mediated trimethylation at H3K27 in the nucleus." (PMID 37880732, 2023). "Based on functional analyses of multiple tumor types, SNHG15 interacted with multiple molecular mechanisms and signaling pathways to impair apoptosis." (PMID 37056344, 2023). "It has been documented that SNHG15 modulates tumor metastasis primarily by regulating EMT, a pro-metastasis process that enabled cells to migrate more efficiently and invade the underlying mesenchyme." (PMID 37056344, 2023). "Overexpression of SNHG15 suggested poor prognosis, which was dramatically related to larger tumor size, lymph node invasion, higher histologic grade, advanced TMN stage, inferior overall survival (OS), and disease-free survival (DFS)." (PMID 37056344, 2023). "Altogether, SNHG15 acted as a sponge of miR-451, a tumor suppressor in gefitinib-resistant LUAD cells." (PMID 32655137, 2020). "By monitoring tumor growth, we discovered that knockdown of SNHG15 slowed down the tumor growth of A549/GR cells in vivo." (PMID 32655137, 2020). "Small Nucleolar RNA Host Gene 15 (SNHG15) was observed with a high expression in the most of tumor tissues." (PMID 32633324, 2020).
tumor (continued). "The tumor volume and weight were lesser in the sh-SNHG15 + DXR group than that in the sh-NC + DXR group, suggesting that SNHG15 knockdown contributed to the inhibitory effect of DXR on the tumor growth in vivo." (PMID 33817274, 2020). "In previous studies, downregulation of SNHG15 was shown to inhibit tumor cell proliferation and invasion and promote apoptosis." (PMID 33817231, 2020). "Further investigations are required to determine the effects of SNHG15 on tumour growth and metastasis in vivo and to illuminate the exact regulatory mechanism of SNHG15 in GC progression." (PMID 31774607, 2020). "Subsequently, using bioinformatics tool, a potential mechanistic route for SNHG15 to promote GBM tumorigenesis was by inhibiting tumor suppressor, miR-627-5p which leads to activation of CDK6." (PMID 31462285, 2019). "It was uncovered that higher expression of SNHG15 was closely related with gender (P = 0.024), larger tumor size (P = 0.030), advanced TNM stage (0.002), and positive lymph node metastasis (P < 0.001)." (PMID 30237435, 2018). "We observed that tumor size (p = 0.017), TNM stage (p = 0.009), and lymph node metastasis (p = 0.001) were positively associated with increased SNHG15 expression." (PMID 29137412, 2017). "Since SNHG15 was closely related to many cellular signaling processes, its expression could be regulated to improve tumor sensitivity." (PMID 37056344, 2023). "A better understanding of the regulatory network of SNHG15 in human tumors might provide neoteric insights regarding tumor pathogenesis and lncRNA-based diagnosis and treatment of human malignancies." (PMID 37056344, 2023). "Considering the pro-tumor role of SNHG15/miR-200A-3p/YAP1/Hippo axis, combined targeting of the YAP1/Hippo signaling pathway might offer a promising treatment direction for PTC." (PMID 37056344, 2023). "SNHG15 impairment was found to compromise tumour cell activity and reduce tumour aggressiveness." (PMID 33968736, 2021). "Additionally, the functional analysis unveiled that SNHG15 knockdown executed tumor-suppressing properties in the deterioration of GC via inhibiting cell proliferation, migration, invasion and facilitating apoptosis." (PMID 33899079, 2021). "Also, gefitinib treatment repressed tumor growth, and knockdown of SNHG15 facilitated the effect of gefitinib." (PMID 32655137, 2020). "Similarly, it was demonstrated that SNHG15 promoted tumour progression in colon cancer by stabilising the transcription factor Slug." (PMID 33243205, 2020). "The results of our functional analysis demonstrated that target genes indirectly affected by SNHG15 may be involved in some of these signaling pathways, and promoted the proliferation, invasion and metastasis of tumour cells." (PMID 33243205, 2020). "In conclusion, these results indicated that SNHG15 could promote CRC tumor growth both in vitro and in vivo." (PMID 30945457, 2019). "Animal experiments showed that up‐regulation of SNHG15 promoted tumor growth in vivo." (PMID 30945457, 2019). "Besides, down-regulation of SNHG15 could inhibit tumor cell proliferation and metastasis, reduce drug resistance and increase apoptosis, indicating a potential molecular target for future tumor therapy." (PMID 37056344, 2023). "Finally, SNHG15 knockdown repressed OS tumor growth in a xenograft tumor model." (PMID 33817231, 2020). "Meanwhile, we measured the expression pattern in OS tissues and interaction between miR-346 and SNHG15 and found an obvious decline in miR-346 in the tumor group compared with normal parts, and a negative correlation could be seen between the expression of miR-346 and SNHG15." (PMID 33817231, 2020). "Therefore, we conducted this meta-analysis and bioinformatic validation to determine whether SNHG15 could be used as a non-invasive prognostic marker of tumours and attempted to reach a consensus regarding the prognostic value of this gene." (PMID 33243205, 2020).